DYNLT1 (dynein light chain Tctex-type 1)
Description:
Component of dynein, a family of motor proteins essential for movement along microtubules (By similarity). Required for structural and functional integrity of cilia (By similarity). Acts as one of several non-catalytic accessory components of the cytoplasmic dynein 1 complex that are thought to be involved in linking dynein to cargos and to adapter proteins that regulate dynein function. Cytoplasmic dynein 1 acts as a motor for the intracellular retrograde motility of vesicles and organelles along microtubules. Binds to transport cargos and is involved in apical cargo transport such as rhodopsin-bearing vesicles in polarized epithelia. Plays a role in neuronal morphogenesis; the function is independent of cytoplasmic dynein and seems to be coupled to regulation of the actin cytoskeleton by enhancing Rac1 activity. The function in neurogenesis may be regulated by association with a G protein beta-gamma dimer. May function as a receptor-independent activator of heterotrimeric G protein signaling; the activation appears to be independent of a nucleotide exchange. Plays a role in regulating neurogenesis; inhibits the genesis of neurons from precursor cells during cortical development presumably by antagonizing ARHGEF2. Involved in the regulation of mitotic spindle orientation (By similarity). Unrelated to the role in retrograde microtubule-associated movement may play a role in the dimerization of cytoplasmic proteins/domains such as for ACVR2B. Binds to the cytoplasmic domain of ACVR2B and, in vitro, inhibits ACVR2B signaling. (Microbial infection) Is involved in intracellular targeting of D-type retrovirus gag polyproteins to the cytoplasmic assembly site.
Synonyms: TCTEL1; TCTEX-1; TCTEX1; CW-1
Tractability: Small molecule: a structure with a bound ligand is known. Antibody: its Gene Ontology location is reachable by antibodies, with high confidence. PROTAC: ubiquitination databases record sites on it; its protein half-life has been measured.
Gene: Protein-coding gene on chromosome 6 (158,636,474 to 158,644,755, reverse strand). Ensembl gene ENSG00000146425.
Subcellular location: Golgi apparatus; Cytoplasm; Cytoplasm, cytoskeleton, spindle
Subcellular location (Human Protein Atlas): Acrosome; Cytosol
Pathways (Reactome):
Disease: Dengue Virus-Host Interactions
Immune System: Neutrophil degranulation
Gene Ontology:
Molecular function: identical protein binding; protein binding; dynein intermediate chain binding
Biological process: intracellular transport of viral protein in host cell; establishment of mitotic spindle orientation; intraciliary retrograde transport; microtubule-based movement; negative regulation of neurogenesis; positive regulation of intracellular transport; positive regulation of mitotic cell cycle spindle assembly checkpoint; regulation of G protein-coupled receptor signaling pathway
Cellular component: cytoplasmic dynein complex; cytoplasmic microtubule; secretory vesicle; cilium; cytoplasm; cytosol; dynein complex; extracellular region; ficolin-1-rich granule lumen; male germ cell nucleus; secretory granule lumen; Golgi apparatus; host cell; spindle
Genetic constraint (gnomAD): Loss-of-function variants: 14 observed, 17.15 expected, observed/expected ratio (o/e) 0.82, 90% interval 0.54 to 1.28. The upper end of that interval is the gene's LOEUF score, 1.28, which puts it in group 5 of 6, group 1 being the genes least tolerant of losing a copy. Missense variants: 121 observed, 129.04 expected, observed/expected ratio (o/e) 0.94, 90% interval 0.81 to 1.09. Synonymous variants: 52 observed, 42.18 expected, observed/expected ratio (o/e) 1.23, 90% interval 0.99 to 1.55.
Homologues: Orthologues: chimpanzee DYNLT1 (100% identical), dog DYNLT1 (100% identical), macaque DYNLT1 (100% identical), rabbit DYNLT1 (99% identical), guinea pig DYNLT1 (96% identical), mouse Dynlt1a (94% identical), mouse Dynlt1b (94% identical), mouse Dynlt1c (94% identical), mouse Dynlt1f (94% identical), rat Dynlt1 (93% identical), tropical clawed frog dynlt1 (84% identical), zebrafish dynlt1a (72% identical), and 3 more. Paralogues in human: DYNLT3 (55% identical), DYNLT2B (26% identical), DYNLT5 (23% identical), DYNLT2 (19% identical), DYNLT4 (16% identical).
Diseases named in the same sentence as DYNLT1 in open-access papers:
DYNLT1 is named in the same sentence as 21 diseases in open-access papers, as found by Europe PMC text mining. Sharing a sentence is not in itself a finding about the gene and the disease. The quoted sentences say what the papers report.
gastric cancer (6 papers, 2020 to 2024). A primary or metastatic malignant neoplasm involving the stomach. "In gastric cancer (GC), DYNLT1 takes part in the miR-15b-3p/Caspase-3/Caspase-9 signaling pathway to promote malignant transformation." (PMID 37081842, 2023). "For example, exosomes secreted by gastric cancer cells transfer miR-15b-3p to recipient gastric cancer cells, promoting the progression of gastric cancer through the dynein light chain Tctex-type 1/caspase-3/caspase-9 signaling pathway." (PMID 33267910, 2020). "In gastric cancer (GC), evidence suggests the involvement of an exo-miR-15b-3p/DYNLT1/Caspase-3/Caspase-9 regulatory network in the pathogenesis." (PMID 38298209, 2024).
breast carcinoma (4 papers, 2022 to 2024). "To explore the underlying mechanism, firstly, we analyzed the genes significantly associated with DYNLT1 in breast cancer using TCGA data and plotted a volcano map of genes significantly positively or negatively associated with DYNLT1 based on correlation." (PMID 37280526, 2023). "DYNLT1 promotes the proliferation, migration, invasion and mitochondrial metabolism in breast cancer cells in vitro and breast tumor development in vivo." (PMID 37280526, 2023). "First, we analyzed breast cancer data from TCGA using bioinformatics methods and found that DYNLT1 was differentially expressed in breast cancer and was significantly higher in tumor tissues than in normal tissues." (PMID 37280526, 2023). "Based on our previous analysis of the TCGA dataset, we found that DYNLT1 was significantly highly expressed in breast cancer and correlated with prognosis." (PMID 37280526, 2023). "In our study, we report that DYNLT1 is an important regulator in mitochondrial metabolism for the development and progression of breast cancer." (PMID 37280526, 2023). "Our data demonstrate that DYNLT1 promotes mitochondrial metabolism to fuel breast cancer development by inhibiting Parkin-mediated ubiquitination degradation of VDAC1." (PMID 37280526, 2023). "Our study showed that knockdown of DYNLT1 significantly inhibited the growth of mouse breast cancer." (PMID 37280526, 2023). "Our data suggest that mitochondrial metabolism can be exploited by targeting the DYNLT1-Parkin-VDAC1 axis to further improve the ability of metabolic inhibitors to suppress breast cancers with limited treatment options, such as TNBC, in the future." (PMID 37280526, 2023). "We found that overexpression of DYNLT1 restored the inhibition of cell proliferation, clone formation, migration and invasion in stable DYNLT1 knockdown MCF-7 or MDA-MB-468 breast cancer cells." (PMID 37280526, 2023). "Together, these results demonstrate that DYNLT1 promotes mitochondrial metabolism by localizing to the mitochondria of breast cancer cells." (PMID 37280526, 2023). "We then knocked down the expression of DYNLT1 in 4T1 breast cancer cells and performed in vivo mouse tumorigenesis assays." (PMID 37280526, 2023). "Survival analysis showed that breast cancer patients with high DYNLT1 expression had a poor prognosis." (PMID 37280526, 2023). "To test this idea, we performed immunofluorescence staining to label DYNLT1 and mitochondria respectively, and the results showed that DYNLT1 was co-localized with the mitochondria in breast cancer cells." (PMID 37280526, 2023). "The role of DYNLT1 in breast cancer development was investigated using in vivo mouse models and in vitro cell assays, including CCK-8, plate cloning and transwell assay." (PMID 37280526, 2023). "Next, we wanted to further explore how DYNLT1 affects mitochondrial metabolism in breast cancer cells." (PMID 37280526, 2023). "The role of DYNLT1 in regulating mitochondrial metabolism in breast cancer development is examined by measuring mitochondrial membrane potential and ATP levels." (PMID 37280526, 2023). "In summary, this study demonstrates that DYNLT1 promotes mitochondrial metabolism to fuel breast cancer development by inhibiting Parkin-mediated ubiquitination degradation of VDAC1." (PMID 37280526, 2023). "In the classification analysis of breast cancer, we found that the expression of DYNLT1 in various subtypes of breast cancer tissues was higher than in normal tissues." (PMID 37280526, 2023). "Then, we examined the effect of DYNLT1 knockdown on the proliferation, clone formation, migration and invasion of breast cancer cells." (PMID 37280526, 2023). "Next, we wanted to further explore the function of DYNLT1 in breast cancer." (PMID 37280526, 2023).
breast carcinoma (continued). "Then, we detected the expression of DYNLT1 in different subtypes of breast cancer cell lines by RT-qPCR and western blot (WB) assay, respectively, and found that DYNLT1 was highly expressed in ER + breast cancer cells, including MCF-7 and T47D, and TNBC cells, including MDA-MB-468 and MDA-MB-231." (PMID 37280526, 2023). "Together, these results collectively suggest that DYNLT1 promotes breast cancer development." (PMID 37280526, 2023). "In vitro and in vivo data demonstrate the oncogenic role of DYNLT1 in breast cancer development." (PMID 37280526, 2023). "Next, we sought to further confirm the oncogenic ability of DYNLT1 in breast cancer." (PMID 37280526, 2023). "Therefore, whether inhibitors targeting DYNLT1 can be combined with VDAC1 inhibitors to achieve a therapeutic effect in breast cancer remains to be further explored." (PMID 37280526, 2023). "Therefore, we speculated whether DYNLT1 can be used as a novel target to regulate breast cancer development and wanted to further explore the mechanism behind it." (PMID 37280526, 2023). "Furthermore, when we explored the effect of DYNLT1 on the ATP levels in the mitochondrial metabolism of breast cancer, we found that the cellular ATP levels were significantly decreased and increased after DYNLT1 knockdown and overexpression, respectively, in breast cancer cells." (PMID 37280526, 2023). "We constructed DYNLT1 stable knockdown cell lines for subsequent studies using ER + MCF-7 and triple negative MDA-MB-468 breast cancer cells, respectively." (PMID 37280526, 2023). "The results showed that DYNLT1, IMMT, RAB2A, and SLC25A5 were unfavorable factors for breast cancer prognosis in the lipid metabolic pathway." (PMID 35919504, 2022). "In addition, Co-IP results showed a significant endogenous interaction between DYNLT1 and VDAC1 in both MCF-7 and MDA-MB-468 breast cancer cells, further suggesting that VDAC1 protein is regulated by DYNLT1." (PMID 37280526, 2023). "DYNLT1 is a new therapeutic target for breast cancer, and the regulatory mechanism between DYNLT1 and VDAC1 in breast cancer has not been reported." (PMID 37280526, 2023). "DYNLT1 (Dynein Light Chain Tctex-Type 1) is a key component of the motor complex that transports cellular cargo along microtubules in the cell, but whether and how DYNLT1 affects mitochondrial metabolism and breast cancer has not been reported." (PMID 37280526, 2023).
breast tumor (2 papers, 2023 to 2024). "Dynein Light Chain Tctex-Type 1 (DYNLT1) is upregulated in breast tumors and is upregulated in breast tumors and is a crucial component of the motor complex that transports cellular cargo along microtubules." (PMID 39179991, 2024). "First, we found that DYNLT1 was upregulated in breast tumors, especially in ER + and TNBC subtypes." (PMID 37280526, 2023).
glioblastoma (2 papers, 2021 to 2023). The most malignant astrocytic tumor (WHO grade IV). "DYNLT1 has been reported to promote glioblastoma progression and is associated with tumor-node-metastasis (TNM) grade." (PMID 37081842, 2023). "The purpose of this study was to determine the role of Tctex1 (DYNLT1, dynein light chain-1) in the pathophysiology of glioblastoma (GBM)." (PMID 34071761, 2021).
male infertility (2 papers, 2023 to 2025). The inability of the male to effect fertilization of an ovum after a specified period of unprotected intercourse. "DYNLT1 encodes part of the motor complex and cytoplasmic dynamic protein and aberrant expression of DYNLT1 has been linked to male infertility in humans." (PMID 39943208, 2025). "In human, absence or lower levels of dynein light chain Tctex-type 1 (DNLT1) have been associated with male infertility." (PMID 37800308, 2023).
ciliopathies (1 paper, 2025). "MAST4 was also recently shown to regulate Tctex-1, or dynein light-chain Tctex-type 1 (DYNLT1), at the primary cilium of mammalian cells, where it accelerated ciliary resorption and is a potential therapeutic target for ciliopathies." (PMID 40299535, 2025).
depression (1 paper, 2012). "The 15 target genes include DYNLT1, GCH1, TOR1B, DISC1, MEF2A and ST3GAL5 that to date were never related to an IFN-α regulation while all of them have been described in association with brain development or depression." (PMID 22701688, 2012).
gastric adenocarcinoma (1 paper, 2020). "Meanwhile, the DYNLT1 gene located at 6q25.3, the long arm of chromosome 6 (6q), has been found to be frequently lost in GC, especially in gastric adenocarcinoma, and may therefore harbor a tumor suppressor gene, which is consistent with the downregulation of DYNLT1 expression in GC found here." (PMID 32039741, 2020).
invasive breast carcinoma (1 paper, 2023). A carcinoma that infiltrates the breast parenchyma. "DYNLT1, IMMT, RAB2A, and SLC25A5 are independent prognostic factors for invasive breast carcinoma and confer a poor prognosis 2)." (PMID 37179822, 2023).
triple-negative breast carcinoma (1 paper, 2023). An invasive breast carcinoma which is negative for expression of estrogen receptor (ER), progesterone receptor (PR), and human epidermal growth factor receptor 2 (HER2). "This study suggests that mitochondrial metabolism can be exploited by targeting the DYNLT1-Parkin-VDAC1 axis to improve the ability of metabolic inhibitors to suppress cancers with limited treatment options, such as triple-negative breast cancer (TNBC)." (PMID 37280526, 2023).
cancer (7 papers, 2011 to 2023). A tumor composed of atypical neoplastic, often pleomorphic cells that invade other tissues. "First, we evaluated the prognostic implications of DYNLT1 in 33 cancer types using data from TCGA by the GEPIA database." (PMID 37081842, 2023). "Our results demonstrated that the mRNA expression of DYNLT1 was higher in most types of cancer tissues compared with paired normal samples, such as BC, GBM, LGG, and PAAD." (PMID 37081842, 2023). "First, we evaluated the mRNA expression of DYNLT1 across 33 cancer types and paired normal samples with data from TCGA by the GEPIA database." (PMID 37081842, 2023). "In fact, a very recent PubMed search using the keywords “Tctex1” or “DYNLT1” and “cancer” resulted in only 12 hits." (PMID 34071761, 2021). "Among them, Cd34, protein tyrosine phosphatase, receptor type, F (Ptprf), Txnrd1, Pgd, Ugt1a1, Gpr137b, and dynein light chain Tctex-type 1 (Dynlt1) were connected in a molecular network of cancer-cell cycle-cell death." (PMID 22039513, 2011). "It is reported that DYNLT1 plays an important role in many biological functions and diseases, such as Huntington's disease, fertilizing potential of human spermatozoa, migration of epidermal cells in hypoxia, autophagy lysosomal degradation, and several types of cancer." (PMID 37081842, 2023). "In addition, DYNLT1 was previously considered an interaction partner of REIC/Dkk-3, inducing apoptosis through its role as a tumor suppressor in various cancer cell lines." (PMID 35919504, 2022). "In addition, DYNLT1 has previously been considered as an interacting partner of REIC/Dkk-3, inducing apoptosis through its action as a multiple cancer cell line tumor suppressor." (PMID 32039741, 2020).
tumor (6 papers, 2020 to 2023). "As expected, the knockdown of DYNLT1 prevented tumor cells from metastasizing to distant organs including the lung and the liver, which prolong the survival period of tumor-burden mice." (PMID 37081842, 2023). "The response biomarkers for immune therapy, such as tumor mutational burden (TMB), between different DYNLT1 expression level BC samples were investigated using data from the TCGA-BRCA cohort utilizing public online tools." (PMID 37081842, 2023). "Furthermore, in vivo experiment was conducted to verify that DYNLT1 knockdown suppressed tumor growth and abolished distant metastasis." (PMID 37081842, 2023). "Mice with DYNLT1 knockdown tumor cells survived a longer period." (PMID 37081842, 2023). "Knockdown of DYNLT1 led to smaller tumor volume and poor survival." (PMID 37081842, 2023). "In this study, we evaluated and validated the expression pattern and prognostic implication of DYNLT1 in BC with multiple public cohorts and BC tumor microarrays (TMAs) of paraffin-embedded tissues collected from the Affiliated Hospital of Jining Medical University." (PMID 37081842, 2023). "Furthermore, in in vivo experiment, we found that DYNLT1 knockdown suppressed tumor growth and abolished distant metastasis." (PMID 37081842, 2023). "Our study is the first to identify Tctex1/DYNLT1 as a tumor-promoting factor in GBM that may furthermore serve as a novel independent prognostic marker for the overall survival of GBM patients." (PMID 34071761, 2021). "Its paralog, DYNLT1, has been found to promote tumor progression." (PMID 32539762, 2020). "We found that DYNLT1, IMMT, RAB2A, and SLC25A5 were tumor biomarkers to assess the prognosis of BRCA patients, and all of them were high-risk genes, and the parameters indicated that 4 genes would make the prognosis of BRCA poorer." (PMID 35919504, 2022). "The results of the qRT-PCR analysis performed on 108 paired GC tumor tissues (R2 = 0.3655, P<0.0001), SGC-7901 cells (R2 = 0.7726, P = 0.0008) and BGC-823 cells (R2 = 0.8703, P<0.0001) found a negative correlation between the expressions of miR-15b-3p and DYNLT1." (PMID 32039741, 2020).
infection (3 papers, 2022 to 2025). The state of being infected such as from the introduction of a foreign agent such as serum, vaccine, antigenic substance or organism. "We observed that luciferase signals were inhibited by the DYNLT1 3′UTR in a dose-dependent manner 1 day post-infection." (PMID 38053173, 2023). "Here we used the same cell infection model to look at possible co-localization between meningococci and the DYNLT1." (PMID 35765029, 2022). "Additionally, the over-expression of DYNLT1 3′UTR resulted in a decrease in ZIKV amounts at early time points post-infection (9 h post-transfection), suggesting that DYNLT1 3′UTR may act on early stages of the virus life cycle." (PMID 38053173, 2023). "Some of these interacting proteins play key roles in cytoskeleton organization (FLNB), vesicular traffic (DYNLT1, USO1), and SUMOylation (UBC9) suggesting an interaction of meningococci with these cellular functions during the intracellular phase of the infection cycle." (PMID 35765029, 2022).
DYNLT1 also shares sentences with these, for which no sentence is quoted: amyotrophic lateral sclerosis (1 paper); atrial fibrillation (1); Bardet-Biedl syndrome (1); Immunodeficiency (1); inflammatory bowel disease (1); ovarian carcinoma (1); prostate carcinoma (1); virus infection (1).